ROR2 (ROR family WNT receptor 2)
Diseases named in the same sentence as ROR2 in open-access papers (continued):
Sharing a sentence is not in itself a finding about the gene and the disease.
atherosclerosis (4 papers, 2020 to 2024). A disease characterized by the build-up of fatty material and calcium deposition in the arterial wall resulting in partial or complete occlusion of the arterial lumen. "In fact, Ror1 and Ror2 are implicated in age-related diseases, including tissue fibrosis, atherosclerosis (or arteriosclerosis), neurodegenerative diseases, and cancers." (PMID 35493090, 2022). "This study aimed to evaluate the therapeutic potential of tetrandrine in high cholesterol diet (HCD)-induced atherosclerosis, in rats, via modulation of miR-34a, as well as, Wnt5a/Ror2/ABCA1/NF-κB pathway and to compare its efficacy with atorvastatin." (PMID 39266573, 2024). "The literature highlighted the role of Wnt5a/Ror-2/ABCA1/NF-κB in the pathogenesis of atherosclerosis." (PMID 39266573, 2024). "This highlights the ability of tetrandrine to ameliorate atherosclerosis in rats via modulating miR-34a as well as Wnt5a/Ror-2/ABCA1/ NF-κB pathway." (PMID 39266573, 2024). "Based on the obtained data, our study aimed to evaluate the therapeutic potential of tetrandrine, in low and high doses, in vitamin D3/HCD-induced atherosclerosis rat model via regulating miRNA-34a and the Wnt5a/Ror2/NF-κB pathway." (PMID 39266573, 2024). "ROR2 was included as a co-receptor of FZD5 because it was proposed as a proinflammatory receptor for Wnt5a in atherosclerosis and lung COPD." (PMID 35622188, 2023). "Therefore, the current study's goal was to evaluate tetrandrine's therapeutic potential in a rat atherosclerosis model by modifying the miR-34a and Wnt5a/Ror2/NF-κB cue." (PMID 39266573, 2024). "We concluded from all of the previous findings that miR-34a together with Wnt5a/Ror2/NF-κB trajectory could have a great role in the pathophysiology of atherosclerosis." (PMID 39266573, 2024). "Finally, PKN3 has been recently demonstrated to play a role in bone resorption downstream of non-canonical Wnt5a/ Ror2 signaling cascade that regulates the secretion of pro-inflammatory cytokines necessary for atherosclerosis development." (PMID 33092266, 2020).
colorectal tumours (4 papers, 2010 to 2023). "Conversely, ROR2 mRNA and protein expression was reported as upregulated in colorectal tumours compared to normal tissue and higher expression was associated with more severe disease and poor outcomes." (PMID 36289823, 2022). "ROR2 mRNA expression was reported to be downregulated in primary colorectal tumours compared to normal colon epithelium in a small patient cohort and functional and in vivo studies pointed to a tumour suppressor role." (PMID 36289823, 2022). "Our lab performed analysis of matched normal tissue and adenomas, along with analysis of colorectal tumours and cell lines and demonstrated epigenetic regulation of ROR2 expression." (PMID 36289823, 2022). "A direct comparison of methylation and expression in the colorectal tumour samples of the cohort revealed that samples with high methylation (beta values > 0.25) had significantly lower ROR2 expression (P < 0.0001)." (PMID 27440078, 2016). "At the protein level, we also observed lower ROR2 levels in tumour samples in most cases; we only detected positive ROR2 staining in 35% of the colorectal tumours analysed." (PMID 20591152, 2010).
gastrointestinal stromal tumor (4 papers, 2014 to 2023). "They found that ROR2 immunoexpression predicts poor overall survival and DSS in patients with gastrointestinal stromal tumor and leiomyosarcoma." (PMID 34440262, 2021).
glioma (4 papers, 2016 to 2022). A benign or malignant brain and spinal cord tumor that arises from glial cells (astrocytes, oligodendrocytes, ependymal cells). "Peng at al reported that in addition to being upregulated in high-grade gliomas, CTHRC1 expression correlated with genes associated with the Wnt Signaling pathway (DVL3, DVL1, DVL2, ROR2, WNT3A, FZD6 and FZD5)." (PMID 36190948, 2022). "Among Wnt ligands, receptors and co-receptors, we found that FZD3, ROR2, and Wnt5a regulate FZD6 overexpression-induced phenotypes in glioma spheres." (PMID 27698350, 2016). "Thus, we examined expression levels of the 19 Wnt ligands, 10 FZDs and co-receptors, LRP6, receptor tyrosine kinase-like orphan receptor 2 (ROR2), and receptor-like tyrosine kinase (RYK) in glioma spheres." (PMID 27698350, 2016).
prostate tumors (4 papers, 2016 to 2022). "IHC staining of tissue array and Oncomine datasets analysis indicated that the gene and protein level of ROR2 is much lower in metastatic prostate tumors as compared with primary tumors or adjacent normal prostate tissues." (PMID 32415173, 2020). "On the other hand, mRNA levels of ROR2, NFKBIA, DUSP6, PLCB3, and SMAD4 are lower in metastatic prostate tumors as compared to primary prostate tumors." (PMID 27191743, 2016). "Compared to the normal prostate tissues or primary prostate tumors, the mRNA levels of DVL3, MAPK9, and CTNNB1 are higher in metastatic prostate tumors while the mRNA level of ROR2 is lower in metastatic prostate tumors." (PMID 27191743, 2016).
chronic lymphocytic leukemia (3 papers, 2018 to 2024). "ROR1 prefers expression over ROR2 in B-cell chronic lymphocytic leukemia (B-CLL) cells." (PMID 38601081, 2024).
diabetes (3 papers, 2017 to 2023). "Specifically, VAT expression of ROR2, FZD7, VANGL2 and PRICKLE1 correlated with that of DSH1,2,3 and DIVERSIN/ANKRD6 in the diabetes group, but not in most cases in the group without diabetes." (PMID 29229927, 2017). "Expression levels of ROR2, FZD7, VANGL2 and PRICKLE1 correlated with each other, and these correlations were statistically significant in subjects with and without diabetes, although in most cases they were much stronger in the group with diabetes." (PMID 29229927, 2017).
gastric tumors (3 papers, 2018 to 2024). "Still, the question of how cancer cells respond to PCP signaling is perplexing, given the downregulation of key receptors such as the concomitant coreceptor ROR2 in many gastric tumors." (PMID 37722040, 2023). "We hypothesized that in this way, the ROR2-low cells, like the gastric tumor cells AGS, could increase their responsiveness to fibroblast-produced WNT5A as they are receiving a functional receptor." (PMID 37722040, 2023). "However, gastric tumors display a high degree of tissue heterogeneity and we find that Ror2 can also enhance β-catenin signaling and consequently cell proliferation." (PMID 30060804, 2018). "Autonomous activation of PCP signaling via Ror2 represses β-catenin signaling and reduces proliferation in AGS cells, suggesting that activation of PCP signaling could be used as a further strategy to inhibit uncontrolled proliferation of gastric tumors." (PMID 30060804, 2018).
non-small cell lung carcinoma (3 papers, 2015 to 2020). A group of at least three distinct histological types of lung cancer, including non-small cell squamous cell carcinoma, adenocarcinoma, and large cell carcinoma. "The ROR2 expression was increased also in human non-small cell lung cancer, and positively correlated with advanced TNM stage." (PMID 32614787, 2020). "The ROR2 expression is also increased in human non-small cell lung cancer (NSCLC) and correlates with an advanced TNM stage, indicating that ROR2 might be an independent prognostic factor in NSCLC." (PMID 32614787, 2020).
osteoarthritis (3 papers, 2017 to 2022). A noninflammatory degenerative joint disease occurring chiefly in older persons, characterized by degeneration of the articular cartilage, hypertrophy of bone at the margins and changes in the synovial membrane. "The expression of ROR2, the co-receptor of Wnt5a, was reported to be enhanced in osteoarthritis and ROR2 overexpression inhibits chondrogenesis, whereas ROR2 silencing induces chondrogenesis." (PMID 35625853, 2022). "Both DOCK2 and ROR2 represent potential drug targets for therapies targeting the biochemical aspect of ACLR and associated osteoarthritis." (PMID 29940858, 2018). "Later in life, aberrant ROR2 signaling may influence processes important for healing damaged ligament or cartilage and could contribute to post-rupture progression of osteoarthritis." (PMID 29940858, 2018). "Indeed, ROR2 is down-regulated in human patients with end-stage osteoarthritis." (PMID 29940858, 2018).
pancreatic ductal adenocarcinoma (3 papers, 2015 to 2023). An infiltrating adenocarcinoma that arises from the epithelial cells of the pancreas. "The Wnt receptors ROR1 and ROR2 are generating increased interest as cancer therapeutic targets but remain understudied in pancreatic ductal adenocarcinoma (PDAC)." (PMID 34763666, 2021). "Moreover, high ROR2 expression was identified in the stroma of 43% of pancreatic ductal adenocarcinoma (PDAC) tissues." (PMID 37722040, 2023). "However, the expression of ROR2 and its functional and prognostic significance have yet to be evaluated in pancreatic ductal adenocarcinoma (PDAC)." (PMID 26259918, 2015).
rheumatoid arthritis (3 papers, 2016 to 2022). A chronic, systemic autoimmune disorder characterized by inflammation in the synovial membranes and articular surfaces. "Aberrant ROR2 signaling appears to play a role in bone loss associated with rheumatoid arthritis and has been shown to be significantly up-regulated in these patients." (PMID 29940858, 2018). "Recently, Wnt5a was highly expressed in synovial tissues in a mouse model of rheumatoid arthritis where inhibition of Wnt5a-Ror2 signaling suppressed bone loss." (PMID 26789270, 2016). "Since Wnt5a expression is associated with rheumatoid arthritis and periodontitis, expression of Wnt5a and its cell surface receptors, Frizzled and receptor tyrosine kinase-like orphan receptor 2 (Ror2), were examined." (PMID 26789270, 2016). "Excess WNT5A-ROR2 signaling may contribute to bone loss in this disease, as shown in rheumatoid arthritis models, where the inhibition of Ror2 signaling suppressed bone loss." (PMID 35052478, 2022).
serous ovarian cancer (3 papers, 2015 to 2022). "In this study, we sought to clarify the effects of ROR2 on high-grade serous ovarian carcinoma (HGSOC) cells and reveal the mechanism." (PMID 31878941, 2019). "The serous ovarian cancer cell line OVCAR3 was chosen for ROR2 knockdown assays due to its expression of both ROR1 and ROR2 at the mRNA and protein level." (PMID 26515598, 2015). "We performed the qRT-PCR analysis of TGFβ components (TGFB1, TGFB2, TGFBR1, TGFBR2), Wnt5A/ROR1/ROR2, and Hippo-related genes (YAP1, TAZ, CCN1, and CCN2) in serous ovarian cancer subtypes (LGSOC, HGSOC, BLSOC) compared to the normal ovary." (PMID 35053353, 2022).
squamous carcinoma (3 papers, 2015 to 2024). "For the first time, we observed higher expression of the tyrosine kinase receptor ROR2 in a metastatic cutaneous squamous carcinoma cell line." (PMID 38565739, 2024). "A previous Kaplan-Meier survival analysis has indicated that ROR2 is an independent prognostic factor for squamous carcinoma and gallbladder adenocarcinoma, and that low ROR2 levels inhibit squamous carcinoma and gallbladder adenocarcinoma growth." (PMID 32614787, 2020). "A previous study indicated that ROR2 might serve as an independent prognostic factor for squamous/adenosquamous carcinoma and gallbladder adenocarcinoma patients, and that ROR2 suppression might inhibit squamous carcinoma and gallbladder adenocarcinoma growth." (PMID 32614787, 2020).
thyroid cancer (3 papers, 2016 to 2024). "Down-regulation of ROR2 decreased thyroid cancer cell proliferation and invasion via suppression of the PI3K/AKT signaling activation." (PMID 32614787, 2020).
autosomal recessive Robinow syndrome (2 papers, 2021 to 2024). Autosomal recessive Robinow syndrome (RRS) is the less common type of Robinow syndrome (RS) characterized by short-limb dwarfism, costovertebral segmentation defects and abnormalities of the head, face and external genitalia. "Pathogenic mutations in ROR2 are involved in two diseases: autosomal recessive Robinow syndrome (RRS, MIM:268310) and autosomal dominant brachydactyly type B1 (BDB1, MIM:113000)." (PMID 33937263, 2021).
brachydactyly type B2 (2 papers, 2017 to 2024). "Mutations in the BMP antagonist Noggin (NOG) and ROR2 cause Brachydactyly type B2 (BDB2)." (PMID 37307827, 2024). "Two closely related forms, Brachydactyly type B2 (BDB2) and BDB1 are caused by mutations in the BMP antagonist Noggin (NOG) and the atypical receptor tyrosine kinase ROR2 that acts as a receptor in the non-canonical Wnt pathway." (PMID 28523267, 2017).
cleft palate (2 papers, 2014 to 2019). Cleft palate is a fissure type embryopathy that affects the soft and hard palate to varying degrees. "It has also been suggested that the Ryk receptor may interact with Ror2 to bind Wnt5a, and mutations in Ryk also cause cleft palate in mice." (PMID 30760477, 2019). "Ror2 knockout mice display craniofacial defects, including cleft palate, further implicating this cascade in the etiology of non-canonical Wnt-signaling-caused orofacial clefts." (PMID 30760477, 2019).
colitis (2 papers, 2015 to 2022). Inflammation of the colon. "Our results support that the Wnt5a-Ror2 axis promotes DSS-induced colitis by enhancing pro-inflammatory cytokine production in the colon." (PMID 26030277, 2015). "Taken together, these results suggested that Ror2 in hematopoietic cells was involved in progression of DSS-induced colitis." (PMID 26030277, 2015). "Here we use dextran sodium sulfate (DSS)-induced colitis in mice as a model for inflammatory diseases and show that disease symptoms were milder in Wnt5a and Ror2 conditional knockout mice than control mice." (PMID 26030277, 2015). "Removing Wnt5a or Ror2 in adult mice suppressed dextran sodium sulfate (DSS)-induced colitis." (PMID 26030277, 2015). "Compared with the Ror2fl/fl mice, both types of Ror2 conditional knockout mice exhibited milder signs and pathological changes following DSS-induced colitis." (PMID 26030277, 2015). "However, DSS treatment reduced Ror2 mRNA expression in B and γδT cells, suggesting that these cells are hard to respond to Wnt5a in DSS-induced colitis." (PMID 26030277, 2015).
colorectal adenoma (2 papers, 2016 to 2021). An adenoma that arises from the colon or rectum. "This is a potential issue for all cell line models as they are cancer cells that are different to the colorectal adenomas in which we believe ROR2 methylation and expression loss first occurs." (PMID 27440078, 2016). "Future research could possibly investigate functional effects of ROR2 loss in colorectal adenomas grown in in vitro organoids." (PMID 27440078, 2016). "In our study, analysis using qRT-PCR found ROR2 expression loss in the majority of both CRC cell lines (n = 23) and colorectal adenoma (n = 6) samples." (PMID 27440078, 2016).
esophageal squamous cell carcinoma (2 papers, 2021 to 2022). Esophageal squamous cell carcinoma (ESCC) is a type of esophageal carcinoma (EC) that can affect any part of the esophagus, but is usually located in the upper or middle third. "ROR1 strongly associates with ROR2, making up the receptor for Wnt5a signaling and activates RhoA through Daam1 in esophageal squamous cell carcinoma (ESCC) and glioblastoma." (PMID 35625853, 2022).
fibrosis (2 papers, 2014 to 2026). the formation of excess fibrous connective tissue in an organ or tissue in a reparative or reactive process. "In addition, Ror2+/− mice exhibited decreased MMP2 levels in damaged kidneys undergoing epithelial-to-mesenchymal transition (EMT) following unilateral ureteral obstruction-induced fibrosis." (PMID 25542006, 2014). "Meflin-deficient mice exacerbated intestinal fibrosis with dysregulated expression of non-canonical Wnt ligand WNT5A and its receptor ROR2." (PMID 42154532, 2026).
glioblastoma (2 papers, 2021 to 2024). The most malignant astrocytic tumor (WHO grade IV). "Interestingly, the pseudokinase RTKs PTK7, ROR1, and ROR2 that activate the Wnt pathway rather than the canonical MAPK and PI3K pathways were mildly to moderately overexpressed in all glioblastoma subgroups." (PMID 34572759, 2021).
head and neck squamous cell carcinoma (2 papers, 2020 to 2023). A squamous cell carcinoma that arises from any of the following anatomic sites: lip and oral cavity, nasal cavity, paranasal sinuses, pharynx, larynx, and salivary glands. "ROR2 expression has been described in non-small cell lung cancer (NSCLC), melanoma, squamous cell carcinoma of head and neck (SCCHN), osteosarcoma, neuroblastoma and renal cell carcinoma, and CAR T-cells with anti-tumour activity have been generated against this target." (PMID 36831514, 2023).
leukemia (2 papers, 2018 to 2021). A malignant (clonal) hematologic disorder, involving hematopoietic stem cells and characterized by the presence of primitive or atypical myeloid or lymphoid cells in the bone marrow and the blood. "Wnt5a, a ligand for ROR1 and ROR2, induced ROR1/ROR2 hetero-oligomerization and enhanced leukemia chemotaxis and proliferation." (PMID 29856777, 2018). "We measured the expression of genes coding RTKs: FLT3, KIT exclusively in leukemia cell lines, PDGFRa, AXL in NB, NTRK1, FGFR3, INSR, ROR2, and RET in both NB and leukemia cells by qRT-PCR, which were top-scoring RTK-coding genes among leukemia and NB cell lines." (PMID 34944663, 2021).
lymph node metastasis (2 papers, 2015 to 2021). "Patients with high ROR2 expression are significantly associated with advanced cancer stage, lymph node metastasis, and a poorer survival rate after the operation." (PMID 34440262, 2021). "High cytoplasmic ROR2 expression in cancer cells was significantly associated with a primary tumor, distant metastasis, and TNM stage, and high stromal ROR2 expression was significantly associated with regional lymph node metastasis and TNM stage." (PMID 26259918, 2015).
lymphoma (2 papers, 2022 to 2024). A malignant (clonal) proliferation of B- lymphocytes or T- lymphocytes which involves the lymph nodes, bone marrow and/or extranodal sites. "Finally, three of the six tumor samples that did not express ALK were positive for ROR2, including two of four ALK- ALCL samples, thus indicating that aberrant ROR2 expression represents a marker for other types of ALK- human lymphoma." (PMID 35246138, 2022). "Therefore, increased expression of MMP9 and ROR2 may play important roles in the survival of lymphoma cells following treatment with TCP plus doxorubicin." (PMID 38514636, 2024).
metastatic melanoma (2 papers, 2010 to 2014). A melanoma that has spread from its primary site to another anatomic site. "ROR2, an orphan tyrosine kinase receptor known to mediate Wnt5A signaling, is upregulated in metastatic melanoma cells with high Wnt5A." (PMID 24281103, 2010).
myelogenous leukemia (2 papers, 2017 to 2018). "Wnt5a and its receptor ROR2 act synergistically to increase autocrine signaling and inhibits canonical Wnt signaling in myeloid leukemia cells." (PMID 29213214, 2017).